NAT10 (N-acetyltransferase 10)
Diseases named in the same sentence as NAT10 in open-access papers (continued):
Sharing a sentence is not in itself a finding about the gene and the disease.
tumor (122 papers, 2015 to 2026). "In vitro studies further demonstrated that NAT10-deficient tumor cells promoted CD8+ T cell proliferation, migration and cytotoxicity." (PMID 41542770, 2026). "NAT10 deficiency in tumor cells increases the infiltration of CD8+ T cells and enhances their cytotoxic functions." (PMID 41542770, 2026). "N-acetyltransferase 10 (NAT10) catalyzes the N4-acetylcytidine (ac4C) modification of mRNA and is associated with tumor occurrence, development and chemotherapy resistance." (PMID 41956987, 2026). "Collectively, Nat10 deficiency reshaped the tumor immune microenvironment by promoting infiltration of effector T cells, enhancing their cytotoxic function, and mitigating their exhaustion, ultimately bolstering antitumor immunity in CRC models." (PMID 41542770, 2026). "Given the observed enrichment of cytotoxic CD8+ T cells in Nat10-deficient tumors, we investigated direct tumor-T cell interactions using in vitro models." (PMID 41542770, 2026). "Clinicopathological correlation analysis showed significant associations between high tumoral NAT10 and advanced tumor characteristics, including tumor node metastasis (TNM), lymph node metastasis and PNI in SYSMH cohort, and TNM and PNI in GDPH cohorts." (PMID 40119353, 2025). "Current evidence confirms that NAT10 dynamically regulates cancer-associated transcriptome homeostasis via ac4C acetylation to drive malignant tumor phenotypes." (PMID 40881352, 2025). "Upregulation of the m5C writer NSUN2 and the ac4C writer NAT10 is implicated in tumor progression through the regulation of cellular metabolic mechanisms." (PMID 39897026, 2025). "In vivo, studies indicated that NAT10 deficiency reversed the promoted tumor growth induced by kynurenine treatment." (PMID 40245789, 2025). "In tumor-bearing rats, kynurenine treatment promoted tumor growth, while NAT10 deficiency reversed these results." (PMID 40245789, 2025). "Mounting evidence suggests that aberrant regulation of NAT10 and ac4C RNA modification is associated with tumor progression." (PMID 39905540, 2025). "Both LINC00623 and NAT10 were found to be highly expressed in PDAC tumor samples, with high NAT10 levels being significantly associated with poorer patient survival rates." (PMID 39817252, 2025). "Collectively, these findings indicate that NAT10 expression is significantly associated with the development of drug resistance and adverse clinical outcomes, such as advanced tumor stage and poor prognosis, in NSCLC." (PMID 41310903, 2025). "Evidence from recent studies has demonstrated that NAT10 and its associated ac4C modification promote the tumor progression of multiple cancer types." (PMID 39640362, 2024). "NAT10-mediated ac4C modifications were linked to 2,156 genes, with 537 ac4C-related genes showing differential expression between normal and tumor." (PMID 39648231, 2024). "We found that the expression levels of both NAT10 mRNA and protein in various tumors were significantly higher than those in normal tissue, and high expression of NAT10 was positively associated with a poor prognosis in tumor patients." (PMID 38308713, 2024). "Aberrant NAT10 expression is associated with the occurrence and prognosis of various cancers; the inhibition of NAT10 suppresses tumor progression." (PMID 37371948, 2023). "The expression levels of NAT10 were confirmed to be associated with tumor tissue immune infiltration, clinical outcome, drug resistance, tumor cell migration and clonogenic ability." (PMID 36949954, 2023). "More importantly, high NAT10 expression was significantly associated with tumor grade, invasion depth, clinical stage and metastasis as well as with inferior overall survival (OS) of GC patients." (PMID 36609449, 2023). "Existing evidence has shown that the NAT10-mediated ac4C modification pattern is associated with tumor stemness and immune cell infiltration." (PMID 35493106, 2022).
tumor (continued). "Multivariate Cox regression survival analysis was further performed among the five mentioned risk factors above, and the results revealed that high expression of NAT10, age ≥ 65 and recurrent tumours were independent risk factors for HNSCC patients’ OS." (PMID 34362389, 2021). "As the only ac4C modification producer, NAT10 is significantly associated with the prognosis of several malignant tumours and potently promotes the tumour progression." (PMID 34362389, 2021). "Above all, this study reported the construction of a risk prediction model and the identification of NAT10 as a critical tumour growth-favoring factor in HNSCC." (PMID 34362389, 2021). "We found that age (≥ 65), tumour site (oral cavity) and tumour type (recurrent) were strongly associated with NAT10 high group." (PMID 34362389, 2021). "These pathways are associated with tumour progression, which indicates the essential role of NAT10 in HNSCC." (PMID 34362389, 2021). "The in vivo results showed that both 2-DG and rapamycin treatments significantly suppressed tumor growth, but overexpression of NAT10 could weaken the anti-tumor effects caused by 2-DG and rapamycin, as indicated by the decreases in tumor size and weight." (PMID 39990211, 2025). "Moreover, ac4C modification of ATP6V0E1 was also observed in lung metastatic tumor tissues from mice, while significantly decreased in the NAT10‐deficient group." (PMID 40729677, 2025). "Furthermore, bioluminescence imaging and analysis in the intraperitoneal metastasis model confirmed that SMAD3 overexpression rescued the majority of the reduced tumor metastasis and growth caused by NAT10 knockdown." (PMID 41476650, 2025). "Studies indicate that ac4C modification strongly correlates with lymph node metastasis in HNSCC, and elevated NAT10 expression may predict tumor susceptibility and unfavorable prognosis." (PMID 41446042, 2025). "Furthermore, in GC patients, univariate Cox regression analysis revealed strong associations between survival and TNM stage; individual tumor (T), node (N), and metastasis (M) classifications; and NAT10 expression." (PMID 39990211, 2025). "Recent research indicates that abnormal expression of NAT10 may be closely associated with drug resistance in tumor cells." (PMID 39764566, 2025). "Specifically, the aberrant activation of NAT10-mediated ac4C have been associated with the progression of tumor malignancies mainly through the regulation of cell proliferation, metastasis, programmed cell death, DNA damage, metabolism, immunosuppression, and chemoresistance." (PMID 40588654, 2025). "Additionally, the strong association between NAT10 and tumor stem cell dedifferentiation underscores its potential importance in PCa progression." (PMID 39648231, 2024). "The NAT10 writer protein is highly expressed in tumor tissues, catalyzing the formation of ac4C residues in RNAs encoded by various cancer-related genes and contributing to tumor evolution." (PMID 38233930, 2024). "Moreover, SiHa tumor xenografts established from cells with NAT10 deficiency showed significantly decreased staining for NAT10, FOXP1, GLUT4, and KHK." (PMID 37818745, 2023). "In TIMER2, after adjustments for tumor purity, NAT10 expression was significantly associated with 42 of 45 immune cell markers in LIHC; however, it was significantly correlated with only 22 gene markers in KIRP, eight gene markers in ACC, 28 gene markers in HNSC and 21 gene markers in PCPG." (PMID 34094911, 2021). "However, the underlying functions and mechanisms of NAT10 in tumor progression and immunology are unclear." (PMID 34094911, 2021). "Collectively, our results indicated that the mechanism underlying the inhibition of NAT10-mediated arrest of cell proliferation and cell cycle progression is a least partially via the upregulation of p16 and p21 tumor suppressors and the downregulation of cell cycle checkpoint proteins in AML cells." (PMID 33425753, 2020).
tumor (continued). "The ac4C writer NAT10 has been implicated in promoting malignant behaviors across multiple cancer types by modulating the ac4C modifications of various mRNAs or proteins, and its expression is strongly associated with tumor aggressiveness and poor clinical outcomes." (PMID 41542770, 2026). "Studies have confirmed that NAT10 and its associated ac4C modification are highly expressed in various tumors; promote the proliferation, metastasis, drug resistance and immunosuppression of tumor cells; and are closely related to the poor prognosis of patients." (PMID 41316475, 2025). "Previous studies have reported that RNA ac4C modification and its acetyltransferase NAT10 contributes to tumor metastasis in various solid tumors which have great propensity to nerve invasion, suggesting a potential association between high NAT10 expression and increased tumor PNI potential." (PMID 40119353, 2025). "However, the underlying functions and mechanisms of NAT10 in tumor progression and tumor immunology remain unclear." (PMID 34094911, 2021). "Collectively, these results suggest that NAT10 induces the secretion of DKK2 by tumor cells and that DKK2 serves as an immune suppressive factor that restricts the recruitment of CD8+ T cells and impairs their cytotoxic function in CRC." (PMID 41542770, 2026). "This pathway was activated in WT tumor cell CM-cultured CD8+ T cells but inhibited in Nat10-KO tumor cell CM-cultured ones." (PMID 41542770, 2026). "Conversely, CD8+ T cells cultured in Nat10-KO tumor cell CM exhibited reduced cholesterol accumulation." (PMID 41542770, 2026). "N-acetyltransferase 10 (NAT10), the sole writer of N4-acetylcytidine (ac4C), is upregulated in multiple cancers and is implicated in tumor pathogenesis." (PMID 41991932, 2026). "Compared with the implantation of WT control cells, the subcutaneous implantation of MC38 Nat10-KO cells into immunodeficient and syngeneic immunocompetent mice suppressed tumor growth." (PMID 41542770, 2026). "Here, we reveal an unexpected immune-evasion mechanism, in which tumor-intrinsic NAT10 orchestrates CD8+ T cell dysfunction via the epigenetic regulation of DKK2." (PMID 41542770, 2026). "In parallel, ac4C, mediated by the acetyltransferase NAT10, fine-tunes translational efficiency and proteostasis, enabling tumor cells to adapt to metabolic and therapeutic stress." (PMID 42120365, 2026). "Correspondingly, Nat10 depletion promoted the lactate dehydrogenase A (LDHA) release in OVA-WT tumor cells cocultured with OT1 CD8+ T cells." (PMID 41542770, 2026). "Functional assays were performed in vitro and in vivo to assess the effects of NAT10 on tumor growth and immune evasion." (PMID 41501889, 2026). "Consistently, Western blot results demonstrated that, relative to the PBS, CuZCeP@NC, and Sono@NC groups, tumor tissues from the Sono@NAT10 group exhibited significantly lower NAT10 and SRSF2 expression, accompanied by a notable upregulation of HDAC10." (PMID 41144699, 2026). "Single-cell analyses reveal tumor- and cell-type-specific expression patterns of RMEs, while supportive functional data suggest a potential biological relevance of NAT10 in HCC." (PMID 41685312, 2026). "Flow cytometric analysis of tumor–T cell cocultures revealed that, compared with their Nat10-KO counterparts, WT tumor cells markedly inhibited CD8+ T cell proliferation." (PMID 41542770, 2026). "Using CellChat, an algorithm for mapping cell-cell communications within scRNA-seq datasets, we demonstrated enhanced ligand-receptor interactions between Nat10-KO tumor cells and TME components, particularly CD8+ T cells." (PMID 41542770, 2026). "Here, we found that NAT10 promotes DKK2 secretion by tumor cells, which increases cholesterol production and impairs the cytotoxic function of CD8+ T cells." (PMID 41542770, 2026). "Mechanistically, NAT10-mediated ac4C modification of DKK2 mRNA in tumor cells maintains DKK2 mRNA stability and promotes DKK2 secretion." (PMID 41542770, 2026).
tumor (continued). "Researches have unveiled that NAT10 exerts immunosuppressive effects within the tumor microenvironment, primarily via three mechanisms." (PMID 40588654, 2025). "The first mechanism is the recruitment effect of NAT10 on immune cells, promoting the infiltration of immune cells in the tumor microenvironment." (PMID 40588654, 2025). "NAT10 levels were also increased in cancer tissues compared with those in non-tumor pancreas tissues, from the Genotype-Tissue Expression (GTEx), the Cancer Genome Atlas (TCGA), and GSE16515 datasets." (PMID 40119353, 2025). "Inhibiting NAT10 reduces tumor cell drug resistance, which shows great potential for cancer therapy." (PMID 39817252, 2025). "In vitro and in vivo models demonstrated that tumor cells overexpression of N-acetyltransferase 10 (NAT10), the writer enzyme of mRNA ac4C modification, enhances PNI in PDAC." (PMID 40119353, 2025). "Further analysis confirmed elevated NAT10 protein levels in tumor tissues, especially in those with PNI." (PMID 40119353, 2025). "Histological analysis via HE staining revealed reduced tumor burden, while IHC analysis demonstrated significantly lower expression levels of tumor biomarkers CK‐19 and Ki67 in liver samples from the NAT10 knockdown group." (PMID 41476650, 2025). "Our data show that NAT10 expression in tumor cells promotes PNI via the ac4C-ITGB5-pFAK-pSrc axis, highlighting the crucial role of ac4C modification in PNI, providing a therapeutic target for preventing PNI and improving the prognosis of patients with PDAC." (PMID 40119353, 2025). "The discovery and characterization of G‐749 as a NAT10 inhibitor to suppress lysosomal dysregulation and tumor metastasis opens up new avenues for cancer drug development." (PMID 40729677, 2025). "As a major ac4C‐modifying enzyme, NAT10 regulates the expression of multiple genes related to tumor progression through acetylation." (PMID 39764566, 2025). "Lack of in vivo validation—xenograft models were able to elucidate the effect of NAT10 on ferroptosis in the tumor microenvironment." (PMID 41189569, 2025). "In summary, our study elucidates a previously unrecognized regulatory mechanism in NPC pathogenesis, characterized by a mutually reinforcing FOXD1/NAT10 positive feedback loop that potently drives tumor progression." (PMID 40999468, 2025). "Next, to study the tumorigenic capacity of G6PD in vivo, we subcutaneously transplanted HepT1 cell-shNC, HepT1 cell-NAT10, and HepT1 cell-NAT10-shG6PD into nude mice and monitored the tumor sizes timely." (PMID 40303290, 2025). "Targeting NAT10's acetylation-dependent regulation of these pathways represents a potential strategy to overcome therapy resistance and enhance tumor cell death." (PMID 40588654, 2025). "Subsequent research will explore how various metabolites influence NAT10‐mediated ac4C acetylation, ultimately promoting malignant tumor progression." (PMID 39764566, 2025). "Cell–cell communication analysis revealed that compared to tumor epithelial cells with low NAT10 expression, those with high NAT10 expression had more intense interactions with T cells, macrophages, and fibroblasts, especially with T cells." (PMID 41203621, 2025). "In summary, future research on NAT10 in the tumor immune microenvironment will help elucidate its role in tumor immune escape and therapy resistance, advancing the field of immunotherapy and offering new strategies for personalized treatment." (PMID 39764566, 2025). "In normal tissues, NAT10 is localized in the nucleus; however, in tumor cells, NAT10 shows a translocated expression, being distributed in the cytoplasm, nucleoplasm, and nuclear membrane, suggesting the complexity and broad range of its functions." (PMID 39764566, 2025). "In vivo experiments have shown that knocking down NAT10 significantly improves the efficacy of PD‐L1 blockade‐mediated tumor regression in vivo." (PMID 39764566, 2025).
tumor (continued). "In summary, NAT10 promotes tumor proliferation by mediating ac4C modification of key oncogenes, enhancing mRNA stability and translation efficiency to drive cancer progression." (PMID 40588654, 2025). "Earlier studies have demonstrated that NAT10 can drive tumor metastasis and drug resistance through its acetyltransferase activity." (PMID 41316475, 2025). "Subsequently, in vitro and in vivo studies showed that the promotion of GC tumor growth by NAT10 was dependent on the activation of glycolysis." (PMID 39990211, 2025). "In BLC, NAT10 promotes tumor growth by upregulating key oncogenes such as B-cell CLL/lymphoma 9-like (BCL9L), SOX4, and AKT1 through ac4C modification." (PMID 41446042, 2025). "NAT10 has been shown to enhance the tumor cell proliferation, metastasis, and invasion abilities of various cancers, resulting in adverse consequences for patient treatment and prognosis." (PMID 39817252, 2025). "In the SYSMH cohort, 57.6% of patients (33 pairs) expressed higher NAT10 mRNA levels in tumor tissues than in adjacent normal pancreas tissues." (PMID 40119353, 2025). "The results revealed that knocking down G6PD significantly inhibited the promoting effect of NAT10 overexpression on tumor growth in the nude mice." (PMID 40303290, 2025). "In essence, NAT10 remodels the tumor metabolic landscape by increasing the flux through glycolytic and biosynthetic pathways, thereby fueling the anabolic demands of rapid proliferation." (PMID 41316475, 2025). "After NAT10 knockdown, the mice received oral gefitinib or osimertinib treatment, and tumor growth was routinely observed." (PMID 41310903, 2025). "The results indicated that Ki-67, N-cadherin, and Vimentin expression levels in HB tumor tissues were enormously lower when NAT10 was knocked down, indicating a marked reduction in the proliferation and invasion capabilities of HB cells." (PMID 40303290, 2025). "Further studies revealed that Khib modification at lysine 823 of NAT10 contributes to promoting its tumor metastasis function." (PMID 39764566, 2025). "In cancer, NAT10-mediated ac4C modification enables tumor cells to repair chemotherapy- or radiotherapy-induced DNA damage, thereby conferring treatment resistance." (PMID 41316475, 2025). "NAT10 specifically catalyzes ac4C epigenetic modifications on oncogenic RNAs and acetylation on proteins in tumor tissues, driving malignant progression." (PMID 40881352, 2025). "High NAT10 expression is observed in bladder urothelial carcinoma (BLCA) and knocking down NAT10 expression significantly inhibits BLCA tumor cell growth and promotes apoptosis." (PMID 39764566, 2025). "Pharmacological inhibition of NAT10 or CRISPR-mediated NAT10 knockout has shown efficacy in suppressing tumor growth and chemoresistance across preclinical models." (PMID 41316475, 2025). "Quantitative IHC analysis revealed higher NAT10 H-scores in tumor tissues and lower CD8+ T-cell H-scores." (PMID 41203621, 2025). "A series of in vitro and in vivo functional studies further confirmed that ATP6V0E1 mediates the effect of NAT10 on lysosomal degradation of E‐cadherin, cell invasion, and tumor metastasis." (PMID 40729677, 2025). "In summary, we systematically outlined the biological characteristics of NAT10 and its effects on tumor proliferation, metastasis, and invasion." (PMID 39817252, 2025). "Inhibition of NAT10 has been shown to suppress tumor growth in some models, positioning it as a potential therapeutic target." (PMID 40870000, 2025). "First, tumor xenograft studies demonstrated that NAT10 silencing significantly inhibited tumor growth, with notable reductions in both tumor size and weight compared to the control group." (PMID 41476650, 2025). "N‐acetyltransferase 10 (NAT10)‐catalyzed N4‐acetylcytidine (ac4C) modification has been reported to drive tumor metastasis." (PMID 40729677, 2025).